NLRP3 (NLR family pyrin domain containing 3)
Diseases named in the same sentence as NLRP3 in open-access papers (continued):
Sharing a sentence is not in itself a finding about the gene and the disease.
Parkinson disease (continued). "Furthermore, recent research has suggested that NLRP3 inflammasome activation in microglia could promote the secretion of exosomes and facilitate the transmission of α-synuclein in Parkinson's Disease (PD)." (PMID 35694441, 2022). "In conclusion, lncZFAS overexpression inhibited the TXNIP/MIB1 E3 ubiquitin ligase/NLRP3 pathway through direct interference with miR590-3p, which shows a novel research avenue in exploring the mechanism of inflammasome activation and pyroptosis in Parkinson’s disease." (PMID 34775541, 2022). "To investigate whether different forms of α-synuclein (α-syn) proteins can induce inflammation and activate the NLRP3 inflammasome, we stimulated with monomeric or aggregated α-syn peripheral blood mononuclear cells of Parkinson disease (PD) patients and age- and sex-matched healthy controls (HC)." (PMID 33867921, 2021). "Furthermore, p38-TFEB pathways inhibited CMA-mediated NLRP3 degradation in Parkinson's disease." (PMID 34930303, 2021). "Inflammation instigated by NLRP3 has been shown to be fundamental to pathophysiological changes in diseases like cryopyrin-associated periodic fever syndrome (CAPS), myocardial infarction, stroke, liver inflammation, type 2 diabetes, Alzheimer's disease Parkinson's disease and aging." (PMID 33718366, 2021). "Finally, inhibition of NLRP3 by MCC950 was also investigated in the context of Parkinson’s disease." (PMID 31892810, 2019). "In Parkinson’s disease, MCC950 treatment significantly decreased the NLRP3 and caspase-1 in the substantia nigra of the brain and elevated the level of the dopamine metabolite 3,4-Dihydroxyphenylacetic acid." (PMID 40906404, 2025). "Accumulation of α-synuclein protein, characteristic of Parkinson’s disease, also stimulates TLR that can activate NLRP3 inflammasome." (PMID 40509336, 2025). "In an animal model of Parkinson's disease, treatment with CBD reduced NLRP3 and caspase 1 levels, as well as improvements in neurological impairment." (PMID 40245261, 2025). "ZYIL1 (Usnoflast) is a selective NLRP3 inflammasome inhibitor that has been shown to decrease CAPS disease activity and improve symptoms in a mouse model of Parkinson’s disease." (PMID 40307577, 2025). "Taken together, our findings suggest that carvacrol mitigated haloperidol-induced Parkinson-like symptoms, partially through the downregulation of TNF-α and NLRP3." (PMID 39910608, 2025). "In mouse models of Parkinson's disease MCC950 prevented neuronal degeneration and in cystic fibrosis it inhibited NLRP3 to reduce inflammation." (PMID 39887961, 2025). "Similarly, NLRP3 inflammasome-associated inflammatory response is not always benefic such as in patients suffering from Parkinson’s disease where NLRP3 inflammasome activation has been associated with neurodegeneration, and that knocking down NLRP3 improve health conditions." (PMID 38644450, 2024). "In Parkinson disease, SGK1 was found overexpressed and SGK1 knockdown suppressed pro‐inflammatory activities of glia through inhibiting the NLRP3‐ and NFκB‐mediated inflammatory pathways." (PMID 39555740, 2024). "NLRP3 inflammasome activation and pyroptosis in primary microglial cells were found to be pivotal for MTPT-induced Parkinson’s disease progression in a murine model." (PMID 34775541, 2022). "The oral administration of the small molecule NLRP3 inhibitor MCC950 in mice inhibits inflammasome activation and effectively relieves Parkinson’s disease-related motor dysfunction, nigrostriatal dopaminergic degeneration, and α-synuclein aggregates." (PMID 36231090, 2022). "DA has been shown to block canonical NLRP3 inflammasome activation and IL-1β secretion induced by various stimuli in mouse microglia and in the MPTP parkinsonism model in vivo, though α-syn-mediated inflammasome activation was not tested." (PMID 35172843, 2022). "Thus, the NLRP3 pathway may provide a new therapeutic avenue for Parkinson’s disease treatment." (PMID 34775541, 2022).
Parkinson disease (continued). "Moreover, α-syn could trigger NLRP3 activation in mice Parkinson’s disease model." (PMID 35431795, 2022). "HOTAIR activates NLRP3‐mediated pyroptosis in SH‐SY5Y cells by negatively regulating miR‐326, thereby promoting neuronal injury in Parkinson's disease." (PMID 34296520, 2021). "Bioinformatics analysis demonstrated that lnc-RNA SNHG1 and mRNA NLRP3 shared the same region to interact with miR-7 in Parkinson’s diseases, suggesting that SNHG1 competes with NLRP3 for binding with miR-7." (PMID 34439798, 2021). "The diarylsulfonylurea-containing compound, MCC950, is a specific inhibitor of NLRP3 inflammasome activation that abrogates ASC oligomerization in human macrophages and in in vivo models of multiple sclerosis and Parkinson ́s disease." (PMID 34829842, 2021). "We hypothesize that patients with Parkinson’s disease exhibit decreased serum levels of SIRT1 and Nrf2 and increased NLRP3 inflammasome levels compared with healthy controls, reflecting impaired antioxidant defense and heightened inflammatory activation." (PMID 41601525, 2026). "Here, we developed a novel NLRP3 inflammasome inhibitor, MCC7840 (also known as Inzomelid or Emlenoflast), and utilized clinically relevant PET-MRI imaging biomarkers to assess its therapeutic efficacy in preclinical models of Parkinson's disease." (PMID 41099134, 2026). "Moreover, various components of the NLRP3 inflammasome, such as Caspase-1, NLRP3 and ASC, are markedly upregulated in microglia within the substantia nigra of Parkinson’s disease patients, suggesting a link between pyroptosis and Parkinson’s disease." (PMID 39058145, 2024). "Additionally, lncRNA NEAT1 impacts Parkinson’s disease pathology by sponging miR-212-3p, which targets AXIN1, while lncRNA SNHG1 exacerbates neuroinflammation in Parkinson’s disease through the miR-7/NLRP3 pathway." (PMID 39280701, 2024). "Studies have shown that α-synuclein (α-Syn), a characteristic pathological protein of Parkinson's disease (PD), may activate the NLR family pyrin domain containing 3 (NLRP3) inflammasome and induce pyroptosis during the progression of the disease." (PMID 38178669, 2024). "NLRP1, NLRP3, and NLRC4 play major roles in neuronal apoptosis in Parkinson’s disease." (PMID 37232753, 2023). "NLRP3 and ASC protein levels are increased in the nigral microglia of PD patients in comparison to control patients and in the striatal microglia of mouse models of parkinsonism in comparison to WT mice." (PMID 35172843, 2022). "Given the positive association between αSyn pathology and microglial NLRP3 inflammasome activation in experimental Parkinsonism, we investigated the contribution of mitochondrial oxidative stress and ERS in the αSynagg-induced NLRP3-dependent microglial activation response." (PMID 34276337, 2021). "Moreover, both p38 inhibitor SB203580 and NLRP3 inhibitor MCC950 not only prevented neurodegeneration in vivo, but also alleviated movement impairment in α-synuclein A53T-tg mice model of Parkinson’s disease." (PMID 34930303, 2021). "However, the combined evaluation of SIRT1, Nrf2, and NLRP3 in patients with Parkinson’s disease has not been thoroughly investigated, particularly in relation to clinical outcomes such as fatigue and quality of life." (PMID 41601525, 2026). "Therefore, our results do not support a role for the NLRP3-inflammasome in Parkinson's disease pathogenesis or as a target for drug development." (PMID 37886468, 2024). "Pathogenic protein aggregates, such as α-synuclein, initiate NLRP3 activation in the microglial cells, activating ASC, caspase-1, and the secretion of proinflammatory cytokines IL-1β and IL-18, and then contribute to the disease progression of Parkinson’s disease." (PMID 36231090, 2022).
Parkinson disease (continued). "MIF (macrophage migration inhibitory factor) reduces the expression of NLRP3 inflammasome and inflammatory factors induced by MPP+ (1-methyl-4-phenylpyridinium) in microglia, reducing DA neuronal damage and exerting protective effects against neuroinflammation induced by Parkinson’s disease." (PMID 36009120, 2022). "Consequently, the absence of dopamine may enhance NLRP3 activation, triggering Parkinson's disease, and NLRP3 ubiquitination emerges as a promising target." (PMID 38317229, 2024). "In addition to helping to determine the underlying mechanism of DA cell death in classical PD, understanding the function of NLRP3 in DA neurons may help distinguish PD from non-classical parkinsonism." (PMID 30131971, 2018). "Inhibition and deficiency of caspase-1 or nod-like receptor family, pyrin domain containing 3 (NLRP3) inflammasome have shown benefits in regulating inflammation and outcomes in AD, experimental autoimmune encephalomyelitis (EAE), TBI, brain ischemia and Parkinson disease (PD)." (PMID 36803990, 2023). "Furthermore, via the activation of inflammasomes, especially NLRP3, the secretion of pro-inflammatory cytokines, such as IL-18 and IL-1β, are stimulated by α-SYN aggregates, a fact that establishes a negative correlation with the development of Parkinson’s disease." (PMID 39861194, 2025).
viral infection (234 papers, 2010 to 2026). "Nevertheless, comprehensive studies and clinical trials are essential to substantiate the precise mechanisms underlying NLRP3 inflammasomes during viral infections." (PMID 38399989, 2024). "Third, this study primarily focused on NLRP3 signaling; however, myocarditis is a multifaceted condition influenced by various factors, such as viral infection, autoimmune response, and genetic predisposition." (PMID 38650023, 2024). "Concordantly, Herc6 deficiency ameliorated NLRP3-dependent inflammation as well as hyperinflammation caused by viral infection." (PMID 37651190, 2023). "The results presented here elucidate the crosstalk between type I IFNs and inflammatory responses and uncover a mechanism by which viral infection causes NLRP3 hyperactivation." (PMID 37651190, 2023). "Concordantly, Herc6 deficiency ameliorates NLRP3-dependent inflammation and hyperinflammation caused by viral infection." (PMID 37651190, 2023). "This study further showed that IFN-γ production was significantly reduced in NLRP3-deficient CD4+ T cells during viral infections." (PMID 37799713, 2023). "Viral infections can lead to an imbalance in intracellular ion concentrations, leading to an abnormal accumulation or loss of K+, Ca2+, and Na+ ions, activating the NLRP3 inflammasome." (PMID 37892135, 2023). "Taken together, these data indicate that Herc6 deficiency attenuated viral infection–induced inflammasome activation by inhibiting NLRP3 expression and therefore ameliorated viral infection–induced hyperinflammation in vivo." (PMID 37651190, 2023). "In virus infections, NLRP3-mediated inflammation and cytokine storms are associated with disease severity; therefore, determining ways to regulate the inflammasome during virus infection is vital for decreasing inflammation and disease severity." (PMID 38249297, 2023). "Due to the range of possible stimuli, NLRP3 has been implicated in a wide range of inflammatory diseases and disorders, including several viral infections such as influenza A virus (IAV)." (PMID 37950278, 2023). "Intriguingly, two independent studies have linked stress granule assembly with inhibition of NLRP3 inflammasome activation in response to various cellular stressors, including viral infection." (PMID 36110852, 2022). "Nod-like receptor family pyrin domain containing 3 (NLRP3) inflammasome has a major part to play in the immune responses during viral infections as it senses the invading pathogen-associated molecular patterns (PAMPs)." (PMID 35077922, 2022). "Respiratory Syncytial Virus (RSV), a viral infection associated with particularly severe outcomes in young children, has been shown to activate the NLRP3 inflammasome, resulting in secretion of IL-1β." (PMID 36298668, 2022). "DDX19A is another DEAD/H-box protein that has been implicated in NLRP3 inflammasome activation in response to viral infection." (PMID 35626643, 2022). "Viral infection causes chronic inflammation and triggers NLRP3 inflammasome activation in immune cells." (PMID 35587188, 2022). "Viral infection-associated NLRP3 inflammasome-dependent inflammation mediates the progression of lung fibrosis by escalating the inflammatory response in immune cells and the cross-talk between immune cells and growth factors." (PMID 34638790, 2021). "There are some pieces of evidence to suggest that the viral infection-associated NLRP3 inflammasome can drive fibrosis." (PMID 34638790, 2021). "Instead we discover that Parkin deficiency increases the innate inflammatory response to viral infection by augmenting mtROS-mediated NLRP3 activation." (PMID 31229895, 2019). "This was further confirmed by western blot analysis showing that NLRP3 deficiency blocked the secretion of mature IL-1β and caspase-1 in supernatant of Park2−/− cells after viral infection." (PMID 31229895, 2019). "Virus infection triggered the association of NLRP3 with Mfn1 and Mfn2 in LPS-primed BMDM in a ΔΨm-dependent fashion." (PMID 31540165, 2019).
viral infection (continued). "NLRP3 variants with reduced penetrance may require an additional inflammatory trigger, or “second hit,” such as a viral infection or vaccination, to precipitate overt clinical disease." (PMID 40927711, 2025). "NLRP3 activation has been linked to both apoptosis and pyroptosis, and its inhibition can alter immune responses and cell survival, suggesting a complex role in viral infections, including IBV." (PMID 40284946, 2025). "The NLRP3 inflammasome is a well-known sensor of various pathogen-associated molecular patterns and damage-associated molecular patterns, including those derived from viral infections." (PMID 39769082, 2024). "Therefore, activating the NLRP3 inflammasome and its associated inflammatory response represent a double-edged sword for the host in its resistance against viral infections." (PMID 37892135, 2023). "Mice deficient in NLRP3 have been shown to exhibit delayed viral clearance and more severely impaired cardiac function than wildtype mice, suggesting a protective role at least during early stage of viral infection." (PMID 36851568, 2023). "NLRP3-dependent inflammasome assembly and consequent IL-1β activation has been shown to be pathogenic in several viral infections contributing to pulmonary fibrosis in cytomegalovirus infected mice and in patients with acute-on-chronic hepatitis B liver failure." (PMID 36189282, 2022). "In light of this, NLRP3 inflammasome-related molecules associated with the viral infection may contribute to the development, preservation of progression, and triggering exacerbation of IPF." (PMID 34638790, 2021). "The NLRP3 inflammasome can be activated by sensing viral components as well as cytosolic danger signals, such as mitochondria injury, protein aggregates, and aberrant ion concentrations, all of which can be caused by a viral infection." (PMID 32133002, 2020). "On the basis of previous studies, we have designed some experiments to explore whether inhibiting NLRP3 inflammasome activation via NF-κB pathway can reduce viral infection and lung injury caused by RSV." (PMID 32047436, 2019). "NLRP3 was also shown to directly associate with mitochondrial mitofusin 2 during viral infection." (PMID 31284572, 2019). "LTB4 via its ability to activate TAK1 could also potentiate TAK1-associated triggering of NLRP3 and consequently enhance inflammasome complex formation to optimize host defense against viral infection." (PMID 26444420, 2015). "Myocarditis can be caused by viral infections, systematic autoimmune diseases, and as a reaction to prescribed medications, and the nucleotide-binding domain leucine-rich repeat pyrin domain-containing 3 (NLRP3) inflammasome is implicated in its pathophysiology." (PMID 42163845, 2026). "However, the overactivation of the NLRP3 inflammasome can also lead to excessive inflammation, which may exacerbate the severity of the viral infection and cause." (PMID 39769082, 2024). "However, the potential role of ISGylation in NLRP3 inflammasome activation and viral infections caused excessive inflammation remains unknown." (PMID 37651190, 2023). "The NLRP3 inflammasome has been identified as a pivotal inflammatory regulator during multiple viral infections, including RSV." (PMID 41349590, 2026). "This comprehensive review synthesizes the diversified landscape of inflammasome activation during viral infections, extending beyond the canonical NLRP3 inflammasome to include specialized sensors such as NLRP6, NLRP9, NLRP1, NLRP12, and NLRC4." (PMID 42198749, 2026). "We have previously demonstrated that viral infection activates the NLRP3 inflammasome in endothelial cells, which is closely associated with increased reactive oxygen species (ROS) as a potential activator." (PMID 41471247, 2025). "Inhibiting aberrant NLRP3 activation offers the potential to alleviate inflammation-driven pathology in diseases ranging from viral infections to metabolic and autoimmune disorders, as well as febrile seizures in children." (PMID 40851698, 2025).